AURKA (aurora kinase A)
Diseases named in the same sentence as AURKA in open-access papers (continued):
Sharing a sentence is not in itself a finding about the gene and the disease.
cancer (continued). "Direct analysis of the relationship between epigenetic modifications on AURKA promoter and transcriptional activity has been investigated in many cancer contexts." (PMID 36067794, 2022). "Emodin also inhibits Aurora kinase A (AURKA), which plays an essential role in proliferation and is involved in cisplatin resistance in various cancer cells." (PMID 35956766, 2022). "After multivariate and LASSO analyses, seven cancer-essential FRGs (ISCU, NFS1, MTOR, EIF2S1, HSPA5, AURKA, and RPL8) were used to construct the risk model." (PMID 35756689, 2022). "Lastly, AURKA is linked to epithelial-to-mesenchymal transition (EMT) and metastatic potential in several cancer." (PMID 36387232, 2022). "Multivariate Cox regression showed that seven cancer-essential FRGs (ISCU, NFS1, MTOR, EIF2S1, HSPA5, AURKA, and RPL8) were significantly associated (p<0.05) with OS." (PMID 35756689, 2022). "AURKA is a widespread protein kinase that plays key roles during cell division and is considered as a potent oncogene and target for cancer therapy." (PMID 34131100, 2021). "Previous evidence also reveals the importance of targeting AURKB/AURKA in cancer cells with activated YAP." (PMID 33805359, 2021). "The main objective of this study is to analyze AURKA expression in 13 common cancers and its role in prognostic and drug resistance." (PMID 34337875, 2021). "All of this evidence favors the idea of AURKA as a target for cancer therapy, and some small molecules targeting AURKA have been discovered." (PMID 33451333, 2021). "We also showed in unique TNBC cells isolated from patient-derived TNBC brain metastasis that dual TGF-β and AURKA pharmacologic targeting reversed cancer plasticity and impaired tumor stemness." (PMID 33674749, 2021). "For the AURKA gene, this value was significantly higher in all subgroups of cancer patients as compared with that in non-cancer patients or healthy subjects (p<0.05)." (PMID 34603753, 2021). "Taken together, these findings demonstrate the essential role of the AURKA/ALDH1 oncogenic axis in inducing cancer cells' self-renewal capacity that is required for MPS growth." (PMID 33674749, 2021). "In an analysis of a highly specific AURKA inhibitor LY3295668 in 560 cancer cell lines, NB was among the most sensitive tumour type tested, with MYC/MYCN amplification identified as among the strongest predictors of sensitivity to this agent." (PMID 34195095, 2021). "Given that overexpression and gene amplification of AURKA have been identified in diverse cancers, small molecule kinase inhibitors of AURKA have attracted considerable interest." (PMID 33451333, 2021). "AURKA promotes tumorigenesis by participating in the cancer cell proliferation, epithelial-mesenchymal transition (EMT), metastasis, apoptosis, and self-renewal of cancer stem cells." (PMID 33451333, 2021). "The overexpression also caused a decrease in expression of cancer-promoting factors EZH2, DNMT1, FOXM1, EGFR, PCNA, AURKA, YAP1, and CDH2." (PMID 34595169, 2021). "Over the years, serious efforts have been taken to exploit specific methods for targeting AURKA in cancer, mainly focused on the design of various inhibitors that are under investigation in clinical trials." (PMID 34884931, 2021). "This work paves the way to the use of function-specific pharmacological inhibitors to counteract the effects of the overexpression of AURKA in cancer." (PMID 33820826, 2021). "The results revealed that the AURKA expression level in all prevalent cancers increased significantly compared to normal samples, and that it was associated with a poor prognosis in part of cancers." (PMID 34337875, 2021).
cancer (continued). "Here, for the first time, we present the data on asynchronous replication of the AURKA gene in peripheral blood lymphocytes from clinically healthy individuals, patients with non-oncological diseases, and patients with several types of cancer." (PMID 34603753, 2021). "AURKA has long been a postulated therapeutic target due to its well-documented overexpression in cancer, although the role it plays in oncogenesis is far from clear." (PMID 34050235, 2021). "This review introduces synthetic lethal interactions between AURKA and its tumor suppressor partners and discusses the potential of AURKA inhibitors in precision cancer medicine." (PMID 34050264, 2021). "Of course, this suggestion requires laboratory approval using cancer cell lines (high AURKA level vs low AURKA level) under commercial available molecules treatment." (PMID 34337875, 2021). "The AURKA gene is usually overexpressed in cancer including MM and its amplification results in chromosome segregation anomalies related to malignant transformation both in vitro and in vivo." (PMID 32978717, 2021). "Activation of AURKA has been demonstrated to play an important role in a wide range of cancers, and numerous AURKA substrates have been identified." (PMID 33451333, 2021). "If a tumor is identified as already having a deficiency in a particular gene, using a drug to inhibit the AURKA enzyme produced by a different gene can lead to cancer cell death." (PMID 34050264, 2021). "In doing so, based on our outcomes and other studies data, the AURKA gene probably has an effect on progressing and developing a cancer cell." (PMID 34337875, 2021). "Mounting evidence have shown that AURKA is involved in the tumorigenesis and progression of multiple types of cancer including solid and hematological malignancies." (PMID 33726773, 2021). "This study showed the overexpression of AURKA in MCF‐10A cancer cell line, and the change of transcriptome have been evaluated (RNA‐seq analysis)." (PMID 34337875, 2021). "Based on our bioinformatics data, JQ1, actinomycin D1, camptothecin drugs decreased the expression level of AURKA in some kinds of cancers." (PMID 34337875, 2021). "AURKA genes was studied to provide cancer therapeutic interventions due to their significant expression in cancer patient samples." (PMID 33732631, 2021). "High-throughput data analysis demonstrated that AURKA was identified as a tumor promoter in all types of cancers." (PMID 34702201, 2021). "Troglitazone also successfully docked into certain protein structures such as lysine-specific demethylase 5B, aurora kinase A, and alpha-tubulin N-acetyltransferase 1, which are connected to cancer." (PMID 33670968, 2021). "For example, miR-4715-3p is inhibited by overexpression of AURKA (aurora kinase A), a serine threonine kinase that has a significant role in mitotic progression in both normal cells and cancers." (PMID 34235152, 2021). "We also showed in unique chemoresistant TNBC cells isolated from patient-derived TNBC brain metastasis that dual TGF-β and AURKA pharmacologic targeting reversed cancer plasticity and enhanced the sensitivity of TNBC cells to DTX-based-chemotherapy." (PMID 33674749, 2021). "Some small molecule inhibitors against AURKA are currently being studied in clinical trials in MM or other cancer patients." (PMID 34260414, 2021). "The functional diversity of AURKA makes it an important drug target in cancer and other pathological conditions." (PMID 34050264, 2021). "Most importantly, AURKA is involved in all of these cancer-related pathways, suggesting the significance of AURKA in these processes and pathways." (PMID 33451333, 2021). "Overall, there is a growing interest in the roles played by AURKA outside of mitosis and their contribution to its cancer-promoting activity." (PMID 34050235, 2021). "AURKA is of strong interest as a therapeutic target for various cancers, but despite extensive testing in clinical trials, alisertib has yet to reach the clinic." (PMID 34050235, 2021).
cancer (continued). "Here, we attempted to identify a deubiquitinase (DUB) that regulates Aurora kinase A (Aurora-A) protein stability and/or kinase activity as a potential cancer therapeutic target." (PMID 33669244, 2021). "Although amplification of the chromosomal region 20q13, where AURKA gene is located, frequently occurs in cancer cells, transcriptional and/or post-translational alterations can also represent possible routes to increased Aurora-A levels." (PMID 33981003, 2021). "The level of peripheral blood lymphocytes with asynchronous replication of the AURKA gene can serve as a basic parameter for the development of a new molecular cytogenetic technology for detecting malignant neoplasms in humans." (PMID 34603753, 2021). "Based on the high expression and significance of AURKA in multiple types of tumors, it is crucial to discover the mechanism of action for AURKA in cancer." (PMID 33451333, 2021). "AURKA shows significantly higher expression in cancer tissues than in normal control tissues for multiple tumor types according to the TCGA database." (PMID 33451333, 2021). "Overexpressed AURKA is discovered in various cancers, such as in colorectal, breast, gastric, ovarian, esophageal and liver cancers." (PMID 34565287, 2021). "Using the cancer genome atlas (TCGA) as well as CCLE and GDSC data, the level of AURKA gene expression and its role in prognosis and its association with drug resistance were evaluated, respectively." (PMID 34337875, 2021). "FBXW7 is a critical tumor suppressor that regulates proteasome-mediated degradation of various oncoproteins, such as cyclin E, c-Myc, Mcl-1, mTOR, Jun, Notch and AURKA in human cancer." (PMID 33450701, 2021). "Paclitaxel was considered a potential drug for cancer therapy due to its inhibition of AURKA and TOP2A." (PMID 34596112, 2021). "For instance, in the current sample, the genes GNAS, GNAQ, and GNA11 were widely altered across cancer types, and these alterations often were accompanied by specific genomic abnormalities in AURKA, CBL, and LYN." (PMID 34150649, 2021). "Collectively, these results indicate that inhibition of AURKA using Alisertib can effectively suppress cancer cell viability, modulate cell cycle distribution and induce apoptosis in UCEC." (PMID 34868993, 2021). "Previous studies indicated that the high level of this gene was vital for tumorigenic capacity and drug resistance in some cancers like breast, lung, and stomach, the way our data showed the connection between the level of AURKA and drug resistance." (PMID 34337875, 2021). "There is overwhelming evidence of overexpression and gene amplification of AURKA in a wide range of cancers." (PMID 33451333, 2021). "These unique features of AURKA make it an important drug target for precision cancer medicine under the circumstances described." (PMID 34050264, 2021). "The role of miR-490 as a tumor suppressor was also proved by its role in the inhibition of the aurora kinase A (AURKA), which is a member of a family of mitotic serine/threonine kinases often associated with high occurrence of cancer." (PMID 34069740, 2021). "The expression matrix of each cancer and the clinical information of each patient were utilized to analyze the relation between the level of AURKA and prognosis in prevalent cancers." (PMID 34337875, 2021).
cancer (continued). "For example, CCNB1 and AURKA were proved to be significantly associated with the prognosis of HCC and HBV-HCC and proposed as hub genes in these cancers." (PMID 33946043, 2021). "Therefore, the AURKA gene contributes in mitotic spindle formation, aneuploidy, and malignant transformation the high level of which could be strongly associated with carcinogenesis and cancer development." (PMID 34337875, 2021). "Withanone is reported to bind to the TPX2/AURKA complex which results in the dissociation of TPX2 from AURKA and disruption of mitotic spindle apparatus in cancer cells." (PMID 33451333, 2021). "Aurora kinase A is known for its overexpression in a variety of cancer types, where its inhibition represents a potential treatment." (PMID 33670968, 2021). "A series of AURKA kinase inhibitors (AKIs) have been produced over the past decades; inhibition of the expression or activity of AURKA by AKIs suppresses cancer cell proliferation, migration and invasion." (PMID 33451333, 2021). "This review introduces the synthetic lethal interactions of AURKA with four different tumor suppressors frequently mutated in cancer: AURKA-SNF5, AURKA-SMARCA4, AURKA-ARID1A, and AURKA-RB1." (PMID 34050264, 2021). "In general, in all BC subtypes, genes associated with resistance, especially AURKA and ERCC1, were frequently expressed, mostly AT, perhaps representing one of the major problems in cancer treatment." (PMID 32558176, 2020). "It is reported that simultaneous inhibition of CHEK1 and AURKA leads to cell cycle arrest and apoptosis of cancer cells." (PMID 32548103, 2020). "Compared with the matched normal tissues, AURKA was significantly upregulated in cancer tissues in 15 out of 18 cancer types." (PMID 32851091, 2020). "For example, it was reported that inhibiting AURKA enhances the chemosensitivity of cancer cells to the taxane and paclitaxel, cisplatin, doxorubicin, and 5-fluorouracil (5-Fu)." (PMID 32851091, 2020). "AURKA inhibition turns the stathmin to a lethal weapon (active, dephosphorylated form) in RB1-deficient cancer cells, killing the cells by disrupting microtubule dynamics." (PMID 33037191, 2020). "We further investigated phosphopeptide signature across five cancer types which led to the prediction of aurora kinase A (AURKA) and kinases-serine/threonine-protein kinase Nek2 (NEK2) as the most activated kinases targets." (PMID 32033228, 2020). "Treatment with AURKA inhibitors decreases MYCN protein levels resulting in suppression of NB tumor growth, making AURKA a suitable target for MYCN-driven cancers." (PMID 33628735, 2020). "AURKA, alone or combined with other factors, can trigger cell malignant transformation and promote the malignant phenotype of cancer cells." (PMID 32851091, 2020). "Identification of protein partners for AURKA can be an important lead to unravel the mechanisms of action for diseases typically cancer and further generate therapeutic drugs and treatment advancement." (PMID 33245732, 2020). "We showed that the AURKA level was adversely correlated with OS in 5 of 15 cancers, including LUAD, KIRP, PAAD, SKCM, and LIHC." (PMID 32851091, 2020). "The AURKA gene has been proven to amplify in 67% of PCa patients with highly aggressive hormone-naive castration resistant cancer." (PMID 32266115, 2020). "The result indicated that AURKA was upregulated in most tested cancer types compared with their normal tissues." (PMID 32851091, 2020). "Apart from AURKA itself, certain interactions between AURKA and other oncogenic factors affect the progression of cancers." (PMID 33050100, 2020). "AURKA promotes cancer by inhibiting apoptosis and augmenting cell survival, cell cycle progression, tumorigenicity, epithelial-mesenchymal transition (EMT) and stem cell-like properties." (PMID 33158056, 2020). "Given the oncogenic potential of AURKA in other cancers and a highly specific inhibitor of AURKA is already available, we focused our further descriptive and functional analyses on AURKA." (PMID 32127951, 2020).
cancer (continued). "Next, we assessed the correlation between the AURKA level and overall survival (OS) in 15 cancer types using the GEPIA." (PMID 32851091, 2020). "The only gene within the other proliferation signaling pathway that showed prognostic potential was AURKA, which is a biomarker for cancer development and progression, and a potential target for therapy in HCC." (PMID 32807134, 2020). "High expression of AURKA commonly correlates with advanced development and poor prognosis of cancers." (PMID 32795325, 2020). "Due to the promising preclinical results, the oral AURKA inhibitor MLN8237 is under clinical evaluation for multiple cancers including relapsed NB." (PMID 33628735, 2020). "Inhibition of AURKA activity activates stathmin and strongly facilitates microtubule depolymerization in RB1-deficient cancer cells, severely impacting the spindle formation and triggering mitotic cell death." (PMID 33037191, 2020). "In summary, this study proposes the agents targeting microtubule dynamics, including AURKA inhibitors, as potential anticancer drugs for the treatment of RB1-deficient cancer, such as SCLC." (PMID 33037191, 2020). "Using Oncomine database, AURKA expression was identified in various human cancers, in both hematological malignancies and solid tumors." (PMID 33245732, 2020). "Specifically, EGFR is a widely studied oncogene with a potential role in cancer therapeutics, six are core genes (AURKA, CDK1, CDT1, PRKDC, RAD51, and XRCC2), six are potential drug targets, and five were identified as drug actionable genes." (PMID 33240468, 2020). "To explore the effect of AURKA on cancer progression and prognosis, we firstly employed the TCGA dataset to analyze the mRNA expression of AURKA in 18 types of tumors." (PMID 32851091, 2020). "AURKA promotes cancer metastasis in HCC by inducing epithelial-mesenchymal transition and cancer stem cell behaviors through the PI3K/AKT pathway." (PMID 32296612, 2020). "We analyzed the expression change of AURKA in pan-cancer and its effect on the prognosis of cancer patients using the TCGA dataset." (PMID 32851091, 2020). "Expression of AURKA was assessed in twenty cancer types and their normal counterparts, and also compared among BC subtypes relative to normal clinical mRNA datasets." (PMID 33245732, 2020). "AURKA has been reported to be overexpressed in various cancers and has been shown to be a promising target in cancer 16-23." (PMID 32127951, 2020). "AURKA functions as an oncogene during the development of multiple malignant tumors by inducing centrosome amplification and genomic instability." (PMID 32851091, 2020). "Here, we report an unexpected, kinase-independent function for AURKA in DNA replication initiation whose inhibition through a class of allosteric inhibitors opens avenues for cancer therapy." (PMID 32652013, 2020). "AURKA, a member of the Aurora kinase family, is an oncogene that plays an important role in cancer stem cell development, epithelial–mesenchymal transition, and distant metastasis." (PMID 30995921, 2019). "AURKAPS1, a long non-coding RNA (lncRNA), is the pseudo-gene of AURKA, which play important roles in the cancer." (PMID 31873123, 2019). "In conclusion, this study highlights a novel epigenetic mechanism that mediates AURKA overexpression in cancer." (PMID 31740746, 2019). "Transient miR-4715-3p reconstitution for 48 h significantly reduced the percentage of cells in G1‐phase, increased the percentage of cells in G2/M, and increased polyploidy in cancer cells similar to effects of AURKA inhibition." (PMID 31740746, 2019). "We found that multiple kinase inhibitors cannot prevent cancer formation in AURKA(WT) and AURKA(V352I) transgenic fish." (PMID 31269749, 2019).